RN7SL771P (RNA, 7SL, cytoplasmic 771, pseudogene)
Gene: Miscellaneous RNA gene on chromosome 7 (140,645,829 to 140,646,126, forward strand). Ensembl gene ENSG00000240173.
Homologues: Orthologues: chimpanzee Metazoa_SRP (99% identical), macaque Metazoa_SRP (85% identical). Paralogues in human: RN7SL1 (79% identical), RN7SL451P (79% identical), RN7SL664P (79% identical), RN7SL2 (79% identical), RN7SL3 (79% identical), RN7SL230P (78% identical), RN7SL408P (78% identical), RN7SL678P (78% identical), RN7SL823P (77% identical), RN7SL126P (77% identical), RN7SL14P (77% identical), RN7SL786P (77% identical), and 704 more.